CNGA2 (cyclic nucleotide gated channel subunit alpha 2)
Description:
Pore-forming subunit of the olfactory cyclic nucleotide-gated channel. Operates in the cilia of olfactory sensory neurons where chemical stimulation of the odorant is converted to an electrical signal. Mediates odorant-induced cAMP-dependent Ca(2+) influx triggering neuron depolarization. The rise of intracellular Ca(2+) levels potentiates the olfactory response by activating Ca(2+)- dependent Cl(-) channels, but it also serves as a negative feedback signal to desensitize the channel for rapid adaptation to odorants. Conducts cAMP- and cGMP-gated ion currents, with permeability for monovalent and divalent cations.
Synonyms: CNG2; OCNC1; CNCA; CNCA1; OCNCa; OCNCALPHA; FLJ46312
Tractability: Small molecule: it belongs to a druggable protein family. Antibody: UniProt predicts a signal peptide or a membrane-spanning region; its Gene Ontology location is reachable by antibodies, with medium confidence.
Gene: Protein-coding gene on chromosome X (151,734,746 to 151,745,564, forward strand). Ensembl gene ENSG00000183862.
Subcellular location: Cell projection, cilium membrane
Pathways (Reactome):
Organelle biogenesis and maintenance: VxPx cargo-targeting to cilium
Sensory Perception: Olfactory Signaling Pathway
Gene Ontology:
Molecular function: cGMP binding; intracellularly cAMP-activated cation channel activity; intracellularly cGMP-activated cation channel activity; intracellularly cyclic nucleotide-activated monoatomic cation channel activity; monoatomic ion channel activity
Biological process: calcium ion transport; monoatomic cation transmembrane transport; potassium ion transport; response to hydrogen sulfide; sensory perception of chemical stimulus; sodium ion transport; monoatomic ion transport; transmembrane transport
Cellular component: ciliary membrane; Golgi-associated vesicle membrane; intracellular cyclic nucleotide activated cation channel complex; non-motile cilium membrane; plasma membrane; membrane
Homologues: Orthologues: chimpanzee CNGA2 (99% identical), macaque CNGA2 (98% identical), dog CNGA2 (95% identical), pig CNGA2 (95% identical), mouse Cnga2 (94% identical), guinea pig CNGA2 (93% identical), rat Cnga2 (93% identical), rabbit CNGA2 (88% identical), tropical clawed frog cnga2 (67% identical), zebrafish cnga2a (67% identical), zebrafish cnga2b (64% identical), Drosophila melanogaster CngA (47% identical), and 3 more. Paralogues in human: CNGA3 (62% identical), CNGA1 (58% identical), CNGA4 (43% identical), CNGB1 (28% identical), CNGB3 (27% identical), HCN1 (23% identical), HCN4 (23% identical), HCN2 (22% identical), KCNH5 (22% identical), KCNH2 (21% identical), KCNH1 (21% identical), KCNH3 (21% identical), and 5 more.
Diseases named in the same sentence as CNGA2 in open-access papers:
CNGA2 is named in the same sentence as 4 diseases in open-access papers, as found by Europe PMC text mining. Sharing a sentence is not in itself a finding about the gene and the disease. The quoted sentences say what the papers report.
Anosmia (3 papers, 2012 to 2018). An inability to perceive odors. "The mice which have mutation in the cyclic nucleotide-gated channel subunit A2 (Cnga2) gene also show general anosmia." (PMID 23126335, 2012). "We initially surmised that the “Super-smeller” phenotype of the Kv1.3−/− mice would predict a reduction in anxiety due to the reported enhancement in stress and anxiety in mouse models of anosmia, such as that of the Cnga2-null lines." (PMID 29615878, 2018). "We then asked how disruption of the cAMP signaling cascade in the olfactory pathway affects neuronal activation using Cnga2-null male mice which show general anosmia and sexual deficits." (PMID 23126335, 2012).
Anxiety (2 papers, 2018 to 2022). Intense feelings of nervousness, tension, or panic often arise in response to interpersonal stresses. "Genetic deletion of cyclic nucleotide gated channel subunit alpha 2 (Cnga2), which is essential for regulating odorant signal transduction, resulted in impaired spatial memory and social behaviors, as well as anxiety-like behavior." (PMID 35927242, 2022).
breast carcinoma (1 paper, 2016). "Moreover, we present evidence that a three-gene set—WNT5A, CNGA2, and IGSF9B—can be used as a signature associated with shorter survival in breast cancer patients." (PMID 28097125, 2016). "Furthermore, we present evidence that a three-gene set—WNT5A, CNGA2 and IGSF9B—was associated with shorter survival in breast cancer patients." (PMID 28097125, 2016).
CNGA2 also shares sentences with these, for which no sentence is quoted: infection (2 papers).